SEPTIN8 (septin 8)
Description:
Filament-forming cytoskeletal GTPase (By similarity). May play a role in platelet secretion. Seems to participate in the process of SNARE complex formation in synaptic vesicles (By similarity). [Isoform 4]: Stabilizes BACE1 protein levels and promotes the sorting and accumulation of BACE1 to the recycling or endosomal compartments, modulating the beta-amyloidogenic processing of APP.
Synonyms: KIAA0202; SEPT8; SEP2; Septin-8
Tractability: Small molecule: a structure with a bound ligand is known. PROTAC: ubiquitination databases record sites on it.
Gene: Protein-coding gene on chromosome 5 (132,750,814 to 132,807,241, reverse strand). Ensembl gene ENSG00000164402.
Subcellular location: Cytoplasm; Cytoplasm, cytoskeleton; Synapse; Cell projection, axon; Cytoplasmic vesicle, secretory vesicle, synaptic vesicle membrane; Presynapse
Subcellular location (Human Protein Atlas): Cytosol; Actin filaments; Annulus; Mid piece; Primary cilium; Principal piece
Gene Ontology:
Molecular function: protein binding; GTPase activity; molecular adaptor activity; GTP binding
Biological process: cytoskeleton-dependent cytokinesis; intracellular protein localization; regulation of SNARE complex assembly
Cellular component: cell division site; cytoplasm; microtubule cytoskeleton; presynapse; septin complex; septin ring; synapse; axon; cytoskeleton; synaptic vesicle membrane
Genetic constraint (gnomAD): Loss-of-function variants: 21 observed, 51.25 expected, observed/expected ratio (o/e) 0.41, 90% interval 0.29 to 0.59. The upper end of that interval is the gene's LOEUF score, 0.59, which puts it in group 2 of 6, group 1 being the genes least tolerant of losing a copy. Missense variants: 535 observed, 644.1 expected, observed/expected ratio (o/e) 0.83, 90% interval 0.77 to 0.89. Synonymous variants: 228 observed, 251.04 expected, observed/expected ratio (o/e) 0.91, 90% interval 0.81 to 1.01.
Homologues: Orthologues: macaque SEPTIN8 (100% identical), chimpanzee SEPTIN8 (99% identical), chimpanzee SEPTIN8 (98% identical), dog SEPTIN8 (98% identical), rat Septin8 (98% identical), mouse Septin8 (98% identical), guinea pig SEPTIN8 (95% identical), pig SEPTIN8 (88% identical), tropical clawed frog septin8 (83% identical), zebrafish septin8a (77% identical), zebrafish septin8b (71% identical), Drosophila melanogaster Septin2 (59% identical), and 1 more. Paralogues in human: SEPTIN11 (70% identical), SEPTIN6 (67% identical), SEPTIN10 (65% identical), SEPTIN14 (55% identical), SEPTIN7 (38% identical), SEPTIN5 (30% identical), SEPTIN2 (29% identical), SEPTIN3 (28% identical), SEPTIN1 (28% identical), SEPTIN9 (28% identical), SEPTIN12 (25% identical), TMEM250 (5% identical).
Diseases named in the same sentence as SEPTIN8 in open-access papers:
SEPTIN8 is named in the same sentence as 11 diseases in open-access papers, as found by Europe PMC text mining. Sharing a sentence is not in itself a finding about the gene and the disease. The quoted sentences say what the papers report.
bladder urothelial carcinoma (1 paper, 2025). "Septin-8 (SEPT8), also inversely correlated with tumor size, has previously been reported in “The Human Protein Atlas” database as a favorable prognostic marker in bladder urothelial carcinoma." (PMID 41441336, 2025).
kidney damage (1 paper, 2021). "One specific limitation of the current work is that we were unable to successfully knock-down SEPTIN8 in the cell culture system; studies that would prove invaluable in further supporting a role of this gene and in understanding its function in kidney damage." (PMID 33483609, 2021). "As detailed below, these findings are supported by our findings in both the rat model, mouse data-sets, and human kidney biopsies, as well as previous work by others, thereby strongly supporting Sept8/SEPTIN8 as a renal injury candidate gene involved in kidney damage." (PMID 33483609, 2021).
neuroblastoma (1 paper, 2021). Neuroblastoma (NB) is the most common solid, extracranial childhood tumor. "In neuroblastoma cells, M5K phosphorylates SEPTIN8 and this could account for the rapid re-localization of SEPTIN8 under hypoxic conditions in the current study." (PMID 33483609, 2021).
SEPTIN8 also shares sentences with these, for which no sentence is quoted: cancer (2 papers); infection (1); kidney disease (1); liver fibrosis (1); osteosarcoma (1); prostate carcinoma (1); renal fibrosis (1); tumor (1).